CD4 (CD4 molecule)
Diseases named in the same sentence as CD4 in open-access papers (continued):
Sharing a sentence is not in itself a finding about the gene and the disease.
infection (continued). "Once inside the infected cell, reverse transcription continues until synthesis of full-length proviral DNA around 8–10 h after infection in immortalized cell lines, and around 12 h after infection in primary CD4+ T cells." (PMID 39000271, 2024). "We found that compared with the corresponding baseline samples, BA.5 breakthrough infection led to augmented BA.5 spike-specific memory CD4+ T cell (5.24-fold, P < 0.0001) and memory CD8+ T cell (18.52-fold, P < 0.0001) responses at T1." (PMID 38456703, 2024). "Here we show that a numerical deficit of CD4 T cells persists in severe cases several months post-infection, particularly in the naïve T cells." (PMID 38212801, 2024). "Human immunodeficiency virus is a retrovirus that attacks the immune system, specifically targeting CD4+T cells, a type of white blood cell crucial for the body’s defense against infections." (PMID 39496030, 2024). "Our data demonstrate that the first three mRNA/LNP-based PanCoVax vaccine candidates (i.e., NSP-2, NSP14, and Nucleocapsid) induced protective CD4+ and CD8+ T-cell-mediated protection against infection with the Delta variant." (PMID 39852809, 2024). "Following a breakthrough infection, the majority of patients had nucleocapsid-specific (32/44 (73%) patients) and membrane-specific CD4 responses (29/44 (66%) patients)." (PMID 39260039, 2024). "During acute human infection, CD4+ T cells upregulate the activation and degranulation markers CD38, CD45RO, and CD107a." (PMID 38793562, 2024). "This successful depletion enabled us to compare the outcome of reinfection to primary infection (IgG vs. naive) and then assess the impact of CD4+ T cell depletion in reinfection (IgG vs. αCD4)." (PMID 39214090, 2024). "Our finding that peripheral Vδ1 T cells contain HIV-1 provirus indicates that infection occurs in vivo despite low CD4 expression." (PMID 39149467, 2024). "Except from a significant increase in SEB-reactive CD4+ T cells among infection-naive patients, polyclonal CD4+ and CD8+ T-cell levels did show any pronounced vaccine-induced dynamics." (PMID 38326340, 2024). "To this end, we immunized C57BL/6 mice with 1000 lap(−) sporozoites and treated them prior to a wild-type challenge infection with antibodies targeting either CD4+ or CD8+ T cells or control antibodies." (PMID 39103697, 2024). "Examining T cell subsets, we noted that while a similar frequency of naïve CD4+ T cells in the meninges upon S. mansoni infection, the infection led to a significant increase in the frequency of effector T cells (TEM, Figure 5Bii)." (PMID 39959586, 2024). "Among the 36 PLHIV, 16 had CD4+T cell counts <50/μL, and out of those, 14 patients were diagnosed with multiple infections." (PMID 38774626, 2024). "We also examined the frequency changes of CD3+CD4+Foxp3+ Tregs in periphery blood after ASFV CADC_HN09 infection." (PMID 38419627, 2024). "In murine experimental L. major infection, CD4+ T cells differentiate into Th1 or Th2 subpopulations that determine infection outcomes." (PMID 38469319, 2024). "Dialysis patients with prior infection had significantly higher spike-specific CD4+ T-cell levels with lower CTLA-4 expression compared to infection-naive patients." (PMID 38326340, 2024). "IKBKB and NF-kB signaling further recruit T-cells to the site of infection, where antigen presentation to CD4+ T-cells can lead to IFN-gamma expression, which has been identified as vital in the host response to intracellular bacteria." (PMID 39062990, 2024). "Replication was reduced by 5-fold at day 50 of infection and was completely controlled in more than 70% of mice by day 55, suggesting the memory CD4 T cells required for resolving persistence take an extended time to differentiate." (PMID 38236791, 2024). "CRTAM+ cells traffic to mucosal and inflammation sites and mature into CD4+ cytotoxic T cells, aiding to protect against infection or induce inflammation." (PMID 38931955, 2024).
infection (continued). "Until then the study of the role of these cells in the infection were mainly aimed at their ability to transfer the virus to the CD4+ T cells." (PMID 39768136, 2024). "In contrast, another gB-based vaccine trial demonstrated that the levels of gB-specific memory B cells were robust at 24 months, and nAbs in fibroblasts and CD4+ T cells were higher than in natural infection in vaccine recipients for up to 4 years." (PMID 38526054, 2024). "Infected cells produce pro-inflammatory cytokines during the infection of dendritic cells, macrophages, and CD4+ T cells." (PMID 39861832, 2024). "In contrast, individuals with initial mild infection exhibited higher naïve and Tem or Temra cells in the virus-specific memory CD4+ and CD8+ T cell subsets." (PMID 38811527, 2024). "However, factors such as CRP, PCT, WBC, neutrophil percentage, CD4+ T cell levels, age, gender, mNGS diagnostic outcomes, infection status, mixed infection, and whether the herpes virus did not reveal significant differences between the Improvement group and the Death group (P > 0.05)." (PMID 38902783, 2024). "With the introduction of cART, procedures like total joint arthroplasty have become safer, though there remains a minor risk of perioperative infection, particularly in patients with uncontrolled HIV or CD4 counts below 400 cells/mm3." (PMID 38790936, 2024). "Analysis of T cell populations in the lungs revealed similar increases in T regulatory cells (Treg) and CD8+ cytotoxic T cells following infection in both genotypes at 7 dpi, while significantly more CD4+ helper T cells were found in TLR7 KO mice." (PMID 39769461, 2024). "IFN-γ expression in CD4+ T cells has been reported as reliable marker of infection and it has been suggested that the number of antigen-specific IFN-γ-secreting effector CD4+ T-cells is correlated with the severity of disease." (PMID 39337287, 2024). "Compared with those of the T-cell subtypes in the liver before infection, the proportions of effector CD4 T, NK, naïve T, and γδ T-cells decreased, whereas the proportions of effector CD8 T, Th1, Th2, and Treg cells increased." (PMID 39590301, 2024). "At any time t during the in vivo infection, S is estimated based on the CD4 and CD8 T-cells drawn from the infected macaque at the time t for the ex vivo assays." (PMID 39255323, 2024). "This suggests that, especially early in infection, the interplay between humoral and cellular immunity is crucial for viral clearance, for example, through CD4+ T-cell co-stimulation of B-cell function." (PMID 38843052, 2024). "CD4 T cells also orchestrate the adaptive response to infection and CD8 T cells recognize and kill infected cells, therefore reducing virus production." (PMID 38491050, 2024). "CHS CD4+ T cells had shown decreased infection compared to WT CD4+ T cells upon HIV-1 exposure, which primarily spreads through cell-to-cell contact involving virion fusion with cell membrane." (PMID 38774881, 2024). "We then show that CD4 became less permissive to SIV in species that experienced long-term endemic infection." (PMID 38014262, 2024). "In patients who had received four vaccine doses, CD4 T cell frequencies were 0.068% (0.034–0.162) before and 0.110% (0.080–0.177) after infection, and CD8 T cell frequencies were 0.039% (0.010–0.145) vs. 0.054% (0.025–0.166)." (PMID 39260039, 2024). "CD28 is critical for T cell proliferation and survival, cytokine production, and CD4+ T cell activation, and its persistent expression is necessary for CD4+ T cell polarization in response to infection." (PMID 38982223, 2024). "Despite the massive presence of eosinophils in early infection, the importance of this cell during the initial steps of Leishmania infection has been overshadowed by a higher number of studies on macrophages, CD4+ T cells, and neutrophils." (PMID 38198296, 2024).
infection (continued). "The percentage of CD4+ T cells producing IL-2 was higher after stimulation with pp65 peptide pool in control subjects with remote infection than in pregnant women with HCMV primary infection at the early and late time points." (PMID 39336935, 2024). "We therefore measured CD4 T cell cytokine production in WT and Bhlhe40-/- mice at day 14 post C. muridarum intravaginal infection." (PMID 38271477, 2024). "UHRF1 deletion decreased active infection in primary activated CD4+ T cells and increased latency reversal in JLat and primary resting CD4+ T cell models." (PMID 38411080, 2024). "Spike-specific CD4+ T cells were low or undetectable by antigen recall assay in both the infection-experienced and naive study groups at study start." (PMID 38716734, 2024). "The NLR, known to be increased with age and associated with bad prognosis during infection, was positively correlated with this CD8 senescence profile whereas the CD4/CD8 ratio was inversely correlated." (PMID 38715114, 2024). "Given the requirement of CD4+ T cells and the central role of the spleen in the clearance of B. microti, we sought to clarify the role of IFNγ secreted by CD4+ T cells on activated splenic macrophages in optimal clearance of the infection." (PMID 39452729, 2024). "The early pathogenesis of MDV is characterized by a burst of productive/restrictive infection in B cells, followed by a latent infection in activated CD4+ T cells that can persist for three weeks prior to reactivation and transformation." (PMID 38879650, 2024). "CXCL9 is upregulated during infection with pathogenic Leptospira and binds to the CXCR3 receptor, which is expressed at all stages of CD4 T-cell development." (PMID 39534703, 2024). "While all models in the 95% confidence set include infection clearance by virus-specific CD4+ T cells, only half include infection clearance by virus-specific CD8+ T cells." (PMID 39575237, 2024). "Our data along with other studies show that CD4 T cells make an important contribution to both primary infection and secondary challenges with B. microti." (PMID 38392861, 2024). "Aiding the integration process is one of Vpr’s first described functions, and its presence in the nucleus seems crucial for the establishment of a productive infection in CD4+ T cells." (PMID 38543785, 2024). "This allowed the usual establishment of lymphocytes in the lung and periphery after the initial infection, but the second exposure to antigen occurred after CD4+ cell depletion." (PMID 38715601, 2024). "The vaccine induced a significant increase in spike-specific CD4+ T-cell levels in both infection-naive (1.76-fold, p = 0.014, Wilcoxon signed rank test) and convalescent patients (1.86-fold, p = 0.006, Wilcoxon signed rank test)." (PMID 38326340, 2024). "In CXCR3 and CCR5 knock-out mice, Chlamydia-specific CD4+ T cells fail to migrate and be retained in genital tract tissues, resulting in reduced clearance of infection compared to wild-type mice." (PMID 39204067, 2024). "The results showed that G. parasuis reduced the CD3, CD4, and CD8 expression at mRNA level in the infection group compared to the control group (p < 0.001) (CD4, p < 0.01)." (PMID 38582846, 2024). "As expected, the proportion of CD4+ T cells at 2-4 weeks post-infection positively correlate with the level of neutralizing antibody titers (R=0.344, p<0.001)." (PMID 39355257, 2024). "Concerning the analysis of the CD4+ T lymphocyte count, there was an association only for rs2069705 (IFNG) directed to the group of individuals with HIV mono-infection (G2)." (PMID 39066175, 2024). "Here, we examine antigen-experienced CD4+ T cells during re-infection in mice, using scRNA-seq/TCR-seq and spatial transcriptomics." (PMID 38944658, 2024).
infection (continued). "In support of these observations, DEGs involved in TCR signaling pathway were correlated with CD8+ and CD4+ T cells, which showed an upregulation and interconnection of key genes in immunological pathways important to infection control and progression of CCC." (PMID 38390336, 2024). "Collectively, these results suggest that γδ T cells play a critical role in promoting Th1 cell differentiation of Plasmodium-specific CD4+ T cells in the acute phase of infection." (PMID 39211036, 2024). "CD8+ T cells in the lungs were considerably increased upon infection, and a mild increase in CD4+ T cells was also noticed." (PMID 39355242, 2024). "Our finding that CD40L blockade during early infection leads to prolonged viremia further supports that CD8+ T cell priming is an essential function of CD4+ T cells and indicates that the CD40L-CD40 pathway plays an important role in hepacivirus infection." (PMID 39392861, 2024). "Factors such as advanced age, peasant, heterosexual infection, long-term infection, and higher viral load significantly impact CD4+T lymphocytes." (PMID 38994006, 2024). "When the AUC was normalized to the base virus SIVmac239, a majority of both the PBMC and CD4+ cell infections performed below baseline." (PMID 39006742, 2024). "HIV-1 is a virus that attacks the immune system, specifically CD4+ T cells, which help the body fight infections." (PMID 39902183, 2024). "To check the potential effect of infection progression through nadir CD4 cells (nCD4) as an indicator in two groups of PWH on two types of therapy, we conducted a t-test for independent samples." (PMID 38923982, 2024). "AREG expression has been reported in epithelial cell layers and various immune cells, including dendritic cells, neutrophiles, and CD4+ T cells, and is constitutively upregulated in response to inflammation or infection." (PMID 38229736, 2024). "Before infection, the total cell number and percentage of IL-17A+ CD4+ T cells (Th17) and IFN-γ+ IL-17A+ T cells (IFN-γ+ Th17) in cLP were significantly lower in water-restricted mice than in control mice." (PMID 38799550, 2024). "The metabolism changes likely depend on the infection stage, as different T cell subsets use different energy sources: Th1, Th2, and Th17 cells favor glycolysis, whereas Tregs and memory T cells (both CD4+ or CD8+) mainly use lipid oxidation." (PMID 39204027, 2024). "The results demonstrate that Omicron-reactive CD4+ T cells are stimulated with both monovalent and bivalent booster vaccines as well as with an Omicron infection." (PMID 39640263, 2024). "After infection, overwhelming immune activation leads to CD4 + T cell depletion, immune dysregulation, and disease progression." (PMID 38227162, 2024). "Of note, CD4+ T cells have been the primary focus of TB research over the last few decades owing to their significance in infection control." (PMID 39650648, 2024). "The LOESS model was used to fit the recovery trend of CD4 cells after infection with different subtypes." (PMID 38994006, 2024). "In the present study we observed greater CD4+ T cell infection frequencies in the EM relative to the CX and ECX, which was primarily driven by increased susceptibility in tissue samples isolated from post-menopausal women." (PMID 39872519, 2024). "Iron-dextran contained infection in mice via NF-κβ TF activation; induced a phenotype resistant to reinoculation with promastigotes (maintained oxidative burst); increased CD4+ T-cell recruitment." (PMID 39211053, 2024). "Upregulation of TIM-3 on exhausted CD8+ and CD4+ T cells upon infection by human immunodeficiency virus type 1 has been reported." (PMID 38343550, 2024). "Considering that the mean duration between pre-infection and the first vaccination was 9 months, these results indicate a degree of persistence in the polyfunctional CD4+T cell response after infection." (PMID 39104410, 2024).
infection (continued). "Especially, intranasal CD4+ T-cell percentages, with about 17% pre-infection, were much lower in the younger, naïve weanlings, which were used for the initial characterization of mucosal immune cells after EHV-1 infection." (PMID 39459849, 2024). "Even though achieving complete virological suppression (<40 RNA copies/mL), 10–40% of ART-treated patients are unable to restore the lost CD4+ T lymphocytes over the infection’s course." (PMID 38932341, 2024). "Relative to controls, the percentage of IFN-γ+ CD4+ T cells (Th1) tended to decrease in water-restricted mice before infection and was comparable in all groups on day 12 post-infection." (PMID 38799550, 2024). "In contrast to B cells and their elicited neutralizing antibodies, CD4+ T cells provide protective immunity that has notable advantages for long-lived protection against infection." (PMID 38543915, 2024). "They identified prior year colonization or infection, a CD4/CD8 ratio below 1, and over 48 h of parenteral nutrition as independent risk factors, achieving an AUROC of 0.844 in external validation." (PMID 38971777, 2024). "Next, an analysis of clinical and laboratory parameters (the number of CD4 lymphocytes) was carried out in patients of different genders, ages, and with different routes of infection." (PMID 39599831, 2024). "In cell culture, HIV-1 Vpr has a modest effect on the infection of cycling primary CD4+ T-cells but a much more pronounced effect on HIV infection of primary macrophages and dendritic cells." (PMID 39205287, 2024). "Rather, CD4 T cells eventually control infection in the SG through the production of the cytokines interferon (IFN)-γ and tumour necrosis factor (TNF)-α, which inhibit viral replication." (PMID 39150988, 2024). "Focusing on the link between CCR5 and cofilin activity, some studies have shown cofilin activation upon HIV gp120 binding to chemokine receptors in blood-resting CD4 T cells during infection." (PMID 38615035, 2024). "Having established that primary infection of WT mice resulted in protection of mice from secondary challenge with B. microti, we examined the importance of CD4 and B cells in this protection using CD4−/− mice and MuMT mice, respectively." (PMID 38392861, 2024). "Further, decreased CD4+ to CD8+ T cell ratios were associated with heavy Sh infection in children and adults (urine eggs >50/mL) compared to ratios in those with light infections." (PMID 39250522, 2024). "Breakthrough infections elicited the formation of N-specific CD4+ T cells in 76% (22/29) of participants, and the levels maintained consistent throughout the observation period." (PMID 39640263, 2024). "Using the mouse model of intraperitoneal infection by B. melitensis, we have previously shown that production of IFN-γ in the spleen presents a peak at 120 hours post-infection and is mainly due to CD4+ T cells." (PMID 39186777, 2024). "As with specific CD4+ T cells towards parental spike, BA.1, BA.2 and BA.4/5-specific CD4+ T-cell levels were significantly higher among convalescent than in infection-naive patients." (PMID 38326340, 2024). "All tested pseudoviruses displayed similar levels of infection on cells expressing human or the ancestral CD4 proteins." (PMID 38014262, 2024). "In the mock treated animals, the highest frequencies of TNFα-producing CD4+ T-cells were detected at day three post-infection preceding the CD8+ T-cell response by two days." (PMID 39472590, 2024). "Following successful transmission, the virus is taken up by DCs at the site of infection and carried to the regional lymph node where CD4+ T cells are infected." (PMID 38400997, 2024). "HIV infection leads to a reduction of CD4 T cells in the gut-associated lymphoid tissue (GALT), a major site for HIV replication during the acute phase of infection, and is responsible for the majority of CD4 T cell depletion." (PMID 39597610, 2024).